TRIM14 (tripartite motif containing 14)
Diseases named in the same sentence as TRIM14 in open-access papers (continued):
Sharing a sentence is not in itself a finding about the gene and the disease.
osteosarcoma (9 papers, 2017 to 2025). A usually aggressive malignant bone-forming mesenchymal neoplasm, predominantly affecting adolescents and young adults. "Kaplan-Meier survival analysis revealed that TRIM14 protein levels are linked with poor prognosis in osteosarcoma patients." (PMID 28205534, 2017). "Consistent with earlier findings, our data showed high expression of TRIM14 in osteosarcoma cell lines and tissues in association with aggressive clinical features and unfavorable prognosis." (PMID 28205534, 2017). "In the current study, we observed upregulation of TRIM14 in human osteosarcoma tissues and cell lines, which was strongly associated with aggressive characteristics and poor patient outcomes." (PMID 28205534, 2017). "To explore the mechanism underlying TRIM14-induced cell growth and metastasis in osteosarcoma cells, we examined its effects on AKT signaling, known to be activated by the TRIM protein family." (PMID 28205534, 2017). "Meanwhile, osteosarcoma cells are affected by TRIM14 and TRIM46 in the context of apoptosis regulation." (PMID 39981097, 2025). "Some TRIM family members, such as TRIM14 in osteosarcoma cells, can influence cell behavior by activating specific signaling pathways." (PMID 39981097, 2025). "TRIM14 overexpression can also boost osteosarcoma cell proliferation, metastasis, and invasion in vitro and enhance tumor growth in vivo, but TRIM14 knockdown produced the reverse outcome." (PMID 37628777, 2023). "For example, target therapy of TRIM14 can inhibit osteosarcoma aggressiveness through the NF-kb signaling pathway." (PMID 36461099, 2022). "Previous report has reported that TRIM14 mediates cell proliferation in osteosarcoma though upregulating the AKT signaling pathway." (PMID 32051827, 2020). "The function of TRIM14 in cancer cell migration and invasion has been described in osteosarcoma and OSCC." (PMID 30555277, 2018). "In conclusion, TRIM14 is markedly overexpressed in osteosarcoma cell lines and clinical samples, and facilitates cell growth and mobility by modulating the AKT pathway." (PMID 28205534, 2017). "Initially, TRIM14 mRNA and protein expression patterns were examined in four osteosarcoma cell lines (Saos-2, U2OS, MG-63, HOS) and the human normal osteoblastic cell line, hFOB 1.19, using qRT-PCR and western blot analyses." (PMID 28205534, 2017). "TRIM14 knockdown suppressed the migration and invasion ability of osteosarcoma cells, and induced downregulation of cyclin D1 and vimentin and simultaneous upregulation of E-cadherin." (PMID 28205534, 2017). "In this study, we showed that TRIM14 is upregulated in human osteosarcoma specimens and cell lines, and correlated with osteosarcoma progression and shorter patient survival times." (PMID 28205534, 2017). "Compared to the corresponding adjacent normal bone tissues, protein levels of TRIM14 were higher in osteosarcoma tissues." (PMID 28205534, 2017). "Ectopic TRIM14 expression induced the growth, migration and invasion of osteosarcoma cells in vitro and promoted tumorigenesis in a mouse model, and conversely, knockdown of TRIM14 had the opposite effects." (PMID 28205534, 2017). "Based on these findings, we propose that TRIM14 accelerates osteosarcoma cell growth, migration and invasion." (PMID 28205534, 2017). "The collective results indicate that knockdown of TRIM14 inhibits osteosarcoma cell proliferation and mobility." (PMID 28205534, 2017). "Accordingly, we propose that TRIM14 promotes the proliferation, migration and invasion of osteosarcoma cells via upregulation of the AKT pathway." (PMID 28205534, 2017). "The results collectively demonstrate that TRIM14 is overexpressed in human osteosarcoma tissues and cell lines." (PMID 28205534, 2017). "To further validate the promotory effects of TRIM14 on osteosarcoma cell growth, and mobility, we suppressed TRIM14 expression in HOS cells using short hairpin RNAs." (PMID 28205534, 2017).
osteosarcoma (continued). "We additionally examined protein expression of TRIM14 using immunohistochemistry (IHC) in 45 paraffin-embedded osteosarcoma tissues." (PMID 28205534, 2017). "To determine the effects of TRIM14 on the migration and invasion abilities of osteosarcoma cells, we performed Transwell assays." (PMID 28205534, 2017). "Our findings collectively suggest that TRIM14 functions as an oncogene by upregulating the AKT signaling pathway in osteosarcoma cells, supporting its potential utility as a therapeutic target for this disease." (PMID 28205534, 2017). "Next, we detected TRIM14 expression in human primary osteosarcoma tumors and adjacent normal bone tissues." (PMID 28205534, 2017). "The correlations between TRIM14 expression and clinicopathologic features of osteosarcoma were further analyzed." (PMID 28205534, 2017). "This activation provides a mechanistic explanation for TRIM14’s role in osteosarcoma cells." (PMID 39981097, 2025). "TRIM14 induces the activation of the AKT/mTOR pathway in osteosarcoma cells." (PMID 33634104, 2020). "Notably, ectopic expression of TRIM14 enhanced the number of migrating and invading osteosarcoma cells." (PMID 28205534, 2017). "Our results clearly support an oncogenic role of TRIM14 in osteosarcoma in vivo." (PMID 28205534, 2017). "Functional studies demonstrated that overexpression of TRIM14 enhances osteosarcoma cell proliferation, clone formation, cell cycle procession, migration and invasion in vitro and promotes tumor growth in vivo, and conversely, its silencing has the opposite effects." (PMID 28205534, 2017). "We further investigated the effects of TRIM14 overexpression on osteosarcoma tumor growth in vivo." (PMID 28205534, 2017). "Clearly, TRIM14 plays an oncogenic role in osteosarcoma progression and may represent an effective therapeutic target for this disease." (PMID 28205534, 2017). "To ascertain whether the proliferation and metastasis of osteosarcoma cells induced by TRIM14 result from activation of the AKT pathway, we examined the growth and invasion abilities of TRIM14-expressing cells after suppression of AKT signaling using siRNA targeting AKT." (PMID 28205534, 2017). "However, the expression levels and biological functions of TRIM14 in osteosarcoma progression remain largely unknown." (PMID 28205534, 2017). "However, the biological role of TRIM14 in osteosarcoma remains to be established." (PMID 28205534, 2017). "Consistent with earlier findings, TRIM14 increased p-AKT, p-mTOR and p-P70S6K levels in osteosarcoma cells, and blocking AKT activity reversed the TRIM14-induced promotory effects on cell growth and metastasis in the current study." (PMID 28205534, 2017). "The data collectively demonstrate that TRIM14 activity is mediated, at least in part, by the AKT pathway, which contributes to its promotory effects on osteosarcoma cell proliferation and invasion." (PMID 28205534, 2017). "The mRNA and protein levels of TRIM14 were significantly increased in osteosarcoma tissues, compared to their adjacent non-tumor tissues." (PMID 28205534, 2017). "Among the osteosarcoma tissues, 67% (30/45) cases were classified as TRIM14-positive, whereas 33% (15/45) stained negative for TRIM14." (PMID 28205534, 2017).
breast cancer (8 papers, 2017 to 2025). A primary or metastatic malignant neoplasm involving the breast. "TRIM14, as a member of the trim family, has been proved to be upregulated in breast cancer, hepatocellular carcinoma, and oral squamous cell carcinoma and can regulate tumor biological behavior through a variety of signaling pathways." (PMID 35652045, 2022). "A recent study has shown that TRIM14 enhanced the STAT3 signaling pathway in breast cancer cells, which plays a critical role in CRC progression." (PMID 30555277, 2018). "For example, LINC00680 was found to be upregulated in docetaxel-resistant breast cancer cells and promotes resistance by sponging miR-432 to upregulate TRIM14 (which affects NF-κB signalling)—this was noted as one mechanism by which lncRNAs contribute to taxane resistance." (PMID 40806254, 2025). "In breast cancer, TRIM14 enhanced tumor cell proliferation via inhibiting apoptosis." (PMID 33982666, 2021). "Furthermore, up-regulation of TRIM14 was found in breast cancer cell lines to promote breast cancer cell proliferation." (PMID 33982666, 2021). "TRIM14 overexpression increased the phosphorylation of STAT3 in breast cancer cells, while it was unclear whether TRIM14 was related to the STAT3 signaling during CRC progression." (PMID 30555277, 2018). "In addition, similar to breast cancer, in PTC, TRIM14 facilitates the ubiquitination and degradation of SOCS1, a negative regulator of STAT3 activation." (PMID 39719450, 2024).
oral squamous cell carcinoma (8 papers, 2017 to 2022). "Similarly, OIP5-AS1 promoted cisplatin resistance via regulating miR-27b-3p/TRIM14 axis in oral squamous cell carcinoma." (PMID 35756672, 2022). "BioMed Research International would like to express concern with the article titled “miR-195-5p Suppresses the Proliferation, Migration, and Invasion of Oral Squamous Cell Carcinoma by Targeting TRIM14” published in October 2017 due to figure duplication, as raised on PubPeer." (PMID 31396535, 2019).
tongue squamous cell carcinoma (7 papers, 2016 to 2022). A squamous cell carcinoma that arises from the tongue. "Overexpression of TRIM14 promoted tongue squamous cell carcinoma by activating the NF-kb signaling pathway." (PMID 35087744, 2021). "Another HOT gene, Trim14 was demonstrated to have oncogenic function in tongue squamous cell carcinoma cell lines by activating the NF-κB pathway." (PMID 27690235, 2016).
melanoma (6 papers, 2021 to 2025). A malignant, usually aggressive tumor composed of atypical, neoplastic melanocytes. "It has been reported that TRIM14 expression is significantly elevated in acute myeloid leukemia, melanoma, and osteosarcoma, all of which can promote tumorigenesis and progression by activating the PI3K/Akt pathway." (PMID 39719450, 2024). "Then, wound healing and transwell assays were performed to explore impacts of overexpression of TRIM14 on the migration and invasion of melanoma cells." (PMID 33982666, 2021). "The expression of TRIM14 in A375 cells was the lowest among melanoma cell lines, and thus the A375 cell line was chosen for overexpression experiments." (PMID 33982666, 2021). "TRIM14 was upregulated in melanoma cell lines to promote melanoma cell proliferation, clone formation, migration, invasion, and epithelial-mesenchymal transition through PI3K/AKT and STAT3 pathways." (PMID 33982666, 2021). "Knockdown of TRIM14 suppressed melanoma cell proliferation, migration, invasion, and melanin synthesis of melanoma cells, while TRIM14 overexpression did the opposite." (PMID 33982666, 2021). "Overexpression of TRIM14 also increased the number of invasive melanoma cells while blocking AKT or STAT3 pathway did the opposite effects." (PMID 33982666, 2021). "Our further wound healing assay showed that TRIM14 overexpression promoted the migration of melanoma cells, while inhibition of AKT or STAT3 pathway with specific inhibitors partially abolished the migration of melanoma cells induced by TRIM14 overexpression." (PMID 33982666, 2021). "What’s more, inhibition of AKT or STAT3 pathway partially abolished the growth of melanoma induced by TRIM14 overexpression." (PMID 33982666, 2021). "Knockdown of TRIM14 inhibits tumor cell proliferation, clone formation, invasion, cycle arrest, and melanin content of melanoma cells." (PMID 33982666, 2021). "Knockdown of TRIM14 reduced the size and weight of tumor, while overexpression of TRIM14 promoted melanoma tumor growth." (PMID 33982666, 2021). "Knockdown of TRIM14 suppressed melanoma cell proliferation, migration, invasion, epithelial-mesenchymal transition, and melanin synthesis." (PMID 33982666, 2021). "Further western blot assay presented a similar result, displaying that TRIM14 was up-regulated in melanoma cells." (PMID 33982666, 2021). "Knockdown of TRIM14 suppressed melanoma cell proliferation, invasion, and epithelial-mesenchymal transition through PI3K/AKT and STAT3 pathways." (PMID 33982666, 2021). "In the present study, we found that TRIM14 is upregulated in melanoma cell lines compared with normal cells." (PMID 33982666, 2021). "In our study, we reported that STAT3 pathway activation was involved in melanoma malignancy mediated by TRIM14." (PMID 33982666, 2021). "Inhibition of PI3K/AKT or STAT3 pathway partially abolished the promotion of melanoma malignancy induced by TRIM14 overexpression." (PMID 33982666, 2021). "MRNA expression of TRIM14 in melanoma cell lines (A375, SK-MEL-24, WM451, WM35) was higher than that in HEMa-LP cells." (PMID 33982666, 2021). "TRIM14 has been shown to promote melanoma malignancy via the PTEN/PI3K/AKT and STAT3 pathways." (PMID 40593126, 2025). "In addition, in melanoma, TRIM14 can also activate the STAT3 pathway to exert its pro-oncogenic effect." (PMID 39719450, 2024). "Whether it is tripartite motif-containing 14 (TRIM14)-promoted melanoma progression or Hey1-promoted melanoma invasion and migration, the PI3K/AKT pathway is an important part." (PMID 36338621, 2022). "Our results showed that TRIM14 was upregulated in melanoma cell lines." (PMID 33982666, 2021). "However, when AKT or STAT3 pathway was blocked, levels of melanin synthesis of melanoma cells mediated by TRIM14 overexpression were decreased." (PMID 33982666, 2021). "The largest difference between the previous finding and ours was that our results revealed TRIM14 might mediate PTEN degradation to activate STAT3 pathway in melanoma." (PMID 33982666, 2021).
melanoma (continued). "In this study, we reported the biological roles of the oncogene TRIM14 in melanoma." (PMID 33982666, 2021). "After confirming AKT and STAT3 pathways were associated with TRIM14-induced melanoma malignancy, we then further explored whether AKT or STAT3 pathway participated in regulating melanin synthesis of melanoma A375 cells mediated by TRIM14." (PMID 33982666, 2021). "Overexpression of TRIM14 had opposite effects on the cellular functions of melanoma cell lines." (PMID 33982666, 2021). "In addition, PTEN/PI3K/AKT and STAT3 pathways participate in regulating TRIM14-induced melanoma development and progression." (PMID 33982666, 2021). "This research supported our results that TRIM14 played oncogenic roles in melanoma." (PMID 33982666, 2021). "In this study, we found that TRIM14 was abnormally upregulated in melanoma cell lines." (PMID 33982666, 2021). "Considering knockdown or overexpression of TRIM14 might play different roles in melanoma cells, we then constructed the TRIM14 overexpression plasmid." (PMID 33982666, 2021). "In summary, our study found that TRIM14 was abnormally overexpressed in melanoma cell lines." (PMID 33982666, 2021). "Nevertheless, the roles of TRIM14 in melanoma remain unknown." (PMID 33982666, 2021). "Furthermore, the expression of TRIM14 in melanoma WM451 and A375 cell lines was the highest." (PMID 33982666, 2021). "Our results presented that pretreated melanoma cells with AKT or STAT3 pathway-specific inhibitor could partially reverse TRIM14 induced tumor cell proliferation, clone formation capacity, invasion, epithelial-mesenchymal transition as well as melanin synthesis capacity." (PMID 33982666, 2021). "Moreover, blocking AKT or STAT3 pathway with a specific inhibitor could partially reverse the promotion of melanoma malignancy mediated by TRIM14 overexpression." (PMID 33982666, 2021). "A previous study found that TRIM14 activates the STAT3 pathway and induces tumor progression in melanoma." (PMID 37628777, 2023). "TRIM14 overexpression activates the AKT and STAT3 pathways to boost melanoma proliferation, which corresponds to our study." (PMID 37628777, 2023). "Overexpression of TRIM14 significantly promoted growth and clone formation capacity of melanoma cells, while blocking AKT or STAT3 pathway partially reversed the promotion of melanoma cell proliferation mediated by TRIM14." (PMID 33982666, 2021). "After that, melanoma cells were pretreated with LY294002, an AKT pathway inhibitor, or SH-4-54, a STAT3 pathway inhibitor, and then transfected with TRIM14 overexpression plasmid." (PMID 33982666, 2021). "Finally, tumor formation in nude mice also showed that TRIM14 could regulate melanoma tumor growth." (PMID 33982666, 2021). "In addition, TRIM14, another member of the TRIM protein family, plays a significant role in regulating melanoma malignancy by impairing the anti-tumor function of PTEN." (PMID 41315179, 2025). "Compared with control or negative control, TRIM14 overexpression increased levels of melanin synthesis of melanoma cells." (PMID 33982666, 2021). "Finally, A375 melanoma cells were transfected with si-TRIM14 or Oe-TRIM14 plasmid with or without pretreatment of LY2940/SH-4-54." (PMID 33982666, 2021).
glioblastoma (4 papers, 2019 to 2025). The most malignant astrocytic tumor (WHO grade IV). "For example, piperlongumine inhibited TRIM14 signaling by activating the p38/MAPK pathway, thereby enhancing the sensitivity of glioblastoma multiforme to the first-line chemotherapeutic agent temozolomide." (PMID 40125551, 2025). "Through loss-of-function and gain-of-function assays, it was shown that TRIM14 induced EMT, migration, and proliferation of glioblastoma cells." (PMID 36139694, 2022).
hepatocellular carcinoma (4 papers, 2018 to 2023). A malignant tumor that arises from hepatocytes. "To this end, we compared the expression of twelve genes either linked to the induction of innate immunity (STAT1, STAT2, PKR) or IFN effector genes (OAS1/2, IFIT1–3, RSAD2, MX1, TRIM14, ISG15) in HCV-infected hepatoma cells and mature iHLCs." (PMID 29497123, 2018).
psoriasis (4 papers, 2022 to 2025). An autoimmune condition characterized by red, well-delineated plaques with silvery scales that are usually on the extensor surfaces and scalp. "Current research on TRIM14 has primarily focused on its roles in tumorigenesis and acute inflammatory responses, with demonstrated involvement in promoting psoriasis and osteoarthritis progression." (PMID 41250673, 2025). "In the correlation analysis between DNA methylation level and psoriasis severity, we found that TRIM14 gene was significantly and negatively correlated, while PRDM16 gene was significantly and positively correlated." (PMID 36193156, 2022). "DNA methylation sequencing results suggest that TRIM14 is hypomethylated in psoriasis, whereas PRDM16 is hypermethylated." (PMID 36193156, 2022). "For further verification, we found that the expression of TRIM14 mRNA increased and PRDM16 mRNA decreased in PBMC of psoriasis patients by RT-PCR and the protein expression detected by ELISA showed the same trend." (PMID 36193156, 2022). "We also found that the methylation levels of TRIM14 and PRDM16 were closely correlated with PASI scores and could serve as potential biomarkers to assess the severity of psoriasis." (PMID 36193156, 2022). "Our study found that methylation levels of genes TRIM14 and PRDM16 may be important markers of psoriasis severity, but the specific mechanism of action of these associated genes requires further research." (PMID 36193156, 2022). "In addition, DNA methylation levels of TRIM14 and PRDM16 may serve as potential biomarkers for assessing the severity of psoriasis." (PMID 36193156, 2022). "Therefore, we speculate that DNA methylation modifications are involved in the expression of TRIM14 and PRDM16 in psoriasis." (PMID 36193156, 2022). "In the correlation analysis between psoriasis methylation level and PASI score, the highest negative correlation was TRIM14, and the highest positive correlation was PRDM16." (PMID 36193156, 2022).